MTOR (mechanistic target of rapamycin kinase)
Diseases named in the same sentence as MTOR in open-access papers (continued):
Sharing a sentence is not in itself a finding about the gene and the disease.
Sepsis (continued). "Remarkably, metabolism-associated pathways, including mTOR, cAMP, AMPK, HIF-1, and cGMP-PKG signaling, were enriched in E-SEP, suggesting that alterations in metabolism might be essential for disease progression in elderly sepsis patients." (PMID 38909272, 2024). "Thus, we got a possible target for drug intervention, further supporting that targeting mTOR may be a new light for sepsis treatment." (PMID 39104632, 2024). "However, the mitigation could be restored by injecting Compound C or MHY1485, suggesting that the AMPK/mTOR pathway was activated in regulating inflammation response during sepsis." (PMID 36694426, 2023). "Research has shown that activating the phosphatidylinositol 3-kinases (PI3K)/AKT/mammalian target of rapamycin (mTOR) pathway and inhibiting the nuclear factor-κβ (NF-κβ) signaling pathway can have a protective effect on organs in the pathological and physiological state of sepsis." (PMID 37359526, 2023). "Hsp22 may inhibit the expression of apoptotic proteins and inflammatory factors by promoting AMPK activation and reducing mTOR phosphorylation levels, and has been shown to significantly improve myocardial injury and inflammation in an LPS-induced sepsis mouse model." (PMID 37629199, 2023). "Short-term mTOR inhibition could also be further studied with the intent to enhance pro-inflammatory responses to LPS as an intervention to sustain anti-bacterial mechanisms needed for recovery in acute sepsis models." (PMID 36028574, 2022). "Importantly, high- and low-dose AE treatment significantly decreased the expression of all three of these genes in treated animals relative to the LPS model group, indicating that AE can suppress the activation of the PI3K-Akt-mTOR pathway in a murine sepsis model." (PMID 35978995, 2022). "In addition, resveratrol (intraperitoneal injection of 60 mg/kg) protected the myocardium in sepsis rat model via activation of the phosphatidylinositol 3-kinases (PI3K)/AKT/mammalian target of rapamycin (mTOR) pathway and inhibition of NF-kB signaling pathway." (PMID 36588685, 2022). "Thus, vitamin C could prevent myocardial cells from LPS-induced death through the ROS-AKT/mTOR-pyroptosis pathway in sepsis." (PMID 36550401, 2022). "Moreover, the stimulation of autophagy with mTOR inhibitors, e.g., anthracyclines or temsirolimus, decreases AKI and mortality, whereas the inhibition of autophagy is associated with worsening apoptosis in the liver in experimental models of sepsis." (PMID 34575294, 2021). "Therefore, the significant downregulation of these miRNAs might suggest the important roles of them in sepsis-induced AKI via involving mTOR and PI3K-Akt signaling pathways." (PMID 31658856, 2019). "Interestingly, sepsis survivors were also distinguished by increased expression of genes related to the mammalian target of rapamycin (mTOR) pathway and autophagy - a mechanism critical for organelle and mitochondrial recycling as well as selective intracellular degradation of invading pathogens." (PMID 25538794, 2014). "Sepsis decreases skeletal muscle protein synthesis in part by impairing mTOR activity and the subsequent phosphorylation of 4E-BP1 and S6K1 thereby controlling translation initiation; however, the relative importance of changes in these two downstream substrates is unknown." (PMID 24945486, 2014). "For the first time, we demonstrate the mTOR-autophagy-ERS-apoptosis axis in sepsis, enriching the targets for future discovery of new sepsis therapies." (PMID 41653334, 2026). "The development of sepsis involves an imbalance between pro- and anti-inflammatory responses, with the PI3K/AKT/mTOR pathway as a crucial inflammatory response." (PMID 40223164, 2025). "Our previous research identified mTOR as a key regulator of T cell metabolism and demonstrated its role in modulating ERS-induced CD4+ T cell apoptosis during sepsis." (PMID 40933998, 2025).
Sepsis (continued). "In sepsis, the PI3K/Akt/mTOR signaling pathway drives immune cells to undergo metabolic reprogramming." (PMID 41041277, 2025). "Studies show that mTOR can exacerbate pyroptosis of CD4+ T cells by negatively regulating the PPARγ-Nrf2 signaling pathway, promoting the occurrence of sepsis-related immune suppression and ultimately resulting in poor clinical prognosis." (PMID 41244772, 2025). "Muscle autophagy signalling is mainly activated through Akt/mTOR inhibition and AMPK activation in the acute phase of sepsis, and it participates directly in muscle catabolism." (PMID 40817441, 2025). "Targeting the mTOR pathway for T cell modulation has shown promise in autoimmune diseases and cancer therapy, with studies demonstrating that mTOR inhibition can mitigate SAI, reduce organ damage, and improve sepsis outcomes." (PMID 40933998, 2025). "Inhibit the mTOR pathway, help alleviate SASP and extend the healthy life and lifespan of sepsis mice." (PMID 40153575, 2025). "In sepsis, the PI3K/Akt/mTOR pathway not only influences inflammatory and immune responses but also alters immune cell metabolism." (PMID 41041277, 2025). "It should be noted that we did not further investigate how high-dose VC affects myocardial apoptosis, inflammation and autophagy during sepsis through MAPK, PI3K/AKT/mTOR and NF-κB pathways." (PMID 38643461, 2024). "PTX3 can attenuate myocardial injury in sepsis due to the down-regulation of apoptosis and autophagy induced by the PI3K/AKT/mTOR pathway." (PMID 38784395, 2024). "A769662 inhibits mTOR signaling pathway by activating AMPK, increasing the expression of the LC3B-I and LC3B-II proteins and alleviating sepsis-induced ALI." (PMID 39161900, 2024). "What’s more, in the treatment of sepsis, the PI3K/AKT/mTOR signaling pathway was described in two ways." (PMID 38643461, 2024). "CaMKIV signaling mediated the autophagic response to sepsis-induced AKI, by inhibiting GSK3β and FBXW7 expression and maintaining mTOR." (PMID 37215112, 2023). "Other pathways and their roles, including mTOR and HIF‐1 signalling pathways, have been investigated in exercised and sepsis‐related laminitis equine subjects, respectively." (PMID 38938916, 2023). "In conclusion, AQP4 aggravates sepsis‐induced neuronal injury and cognitive dysfunction by inhibiting PPAR‐γ/mTOR‐dependent autophagy and activating inflammatory response in astrocytes." (PMID 36922751, 2023). "Previous research has found that when applied to sepsis, XBJ blocked the phosphorylation of the PI3K/AKT/mTOR signaling pathway." (PMID 37219401, 2023). "Hence, in LPS-induced systemic inflammation (and even sepsis), whether J147 can regulate mitochondrial function, affect microglial polarization, and activate the CAMKK2/AMPK/mTOR pathway, thereby alleviating organ dysfunction in sepsis, warrants further exploration." (PMID 37676534, 2023). "The results showed that sepsis miR-506-3p OE group had significantly decreased expressions of PIK3CA, PI3K and mTOR (p < 0.01), and significantly increased expressions of Beclin, LC-3II and ATG5 compared with sepsis miR-506-3p OE NC group (p < 0.01)." (PMID 37285838, 2023). "Inversely, knocking down miR-130b-3p activated the AMPK/mTOR signaling pathway and upregulated the protein expression level of LC3A/B, and downregulated SQSTM1 in sepsis-induced cardiomyopathy mice." (PMID 37705752, 2023). "We used caecal ligation and puncture (CLP) and lipopolysaccharide (LPS) stimulation to induce a sepsis model, using key pathways (PI3K/AKT/MTOR) and Warburg effect-related indicators." (PMID 37434129, 2023). "Mir-214 protected against sepsis-induced AKI by decreasing oxidative stress and suppressing autophagy via regulation of the PTEN/AKT/mTOR pathway." (PMID 37215112, 2023). "After normalising the grey values, the expressions of p-PI3K/PI3K, p-AKT/AKT, p-MTOR/MTOR, HIF-1α, and PDK1 were decreased in CLP and LPS-induced sepsis, and the Warburg effector pathway was inhibited." (PMID 37434129, 2023).
Sepsis (continued). "As the expression of mTOR, T-bet and IFN-γ, and PD-1 by CD4+T cell fluctuates with sepsis severity, and the four markers displayed significant predictive significance for prognosis, which is consistent with our previous reported results." (PMID 35898496, 2022). "Hence, we hypothesized that mTOR likely affects apoptosis by regulating T cell ERS during sepsis." (PMID 35759162, 2022). "In sepsis, CYT107 has an impact on immunometabolism via improving mTOR signaling, GLUT1 surface expression, and glucose uptake by T cells and targeting this metabolism pathway showed promising results in a phase II clinical on patients in septic shock." (PMID 36530909, 2022). "A previous study successfully showed that TG attenuates sepsis‐induced myocardial dysfunction by inhibiting myocardial autophagy by silencing PTEN expression and acting on the AKT/mTOR pathway." (PMID 36308410, 2022). "The inhibition of phosphatidylinositol 3 kinase (PI3K) activity and Akt kinase (which inhibits mTOR and proteosynthesis) is the signal for UPS activation and initiation of proteolysis in all cells in a catabolic state (sepsis, inflammation, immobility)." (PMID 35955530, 2022). "Reinforcing this observation, genes involved in the MAPK, mTOR, TLR2/MyD88 and JAK/STAT pathway are also up-regulated in the LPS group, as recently described in sepsis patients, confirming the pertinence of such approaches." (PMID 35742875, 2022). "To determine the role of mTOR in ERS-induced CD4+ T cell apoptosis, we constructed a sepsis model with T cell-specific mTOR and TSC1 gene knockout mice." (PMID 35915740, 2022). "Circulating serum miR-92a was found to be elevated in patients with sepsis-induced ARDS, and miR-92a inhibitors inhibited LPS-induced apoptosis and inflammatory responses via the Akt/mTOR pathway." (PMID 35726235, 2022). "Resveratrol, a natural phenolic compound, has also been found to have a significant protective effect in sepsis and protects the heart in sepsis by activating the Nrf2 and PI3K/AKT/mTOR pathways and inhibiting the NF-κB pathway." (PMID 35983185, 2022). "Sepsis and disuse of muscle reduce IGF-1 activity, via reduced mTOR activity, which results in decreased muscle protein synthesis." (PMID 35955530, 2022). "Significant differences were observed in the metabolic signaling pathways, including the mTOR, PI3K/AKT, and FoxO pathways, between the sepsis and sepsis-AW groups." (PMID 36016684, 2022). "Through the intervention of mTOR, the stress and damaged state of CD4+ T cells in sepsis were improved, CD4+ T cell apoptosis was reduced, and the prognosis of the host was improved." (PMID 35915740, 2022). "We found that ROS accumulation in sepsis led to ERS occurrence and that the mTOR pathway operating downstream of ERS induced CD4+ T cell apoptosis." (PMID 35915740, 2022). "We have previously confirmed that mTOR is involved in the immunosuppression of sepsis and that the apoptosis of CD4+ T cells can be attenuated by mTOR intervention." (PMID 35915740, 2022). "A study of sepsis-induced AKI mechanism showed that miR-15a-5p, miR-15b-5p, and miR-16-5p were involved in the mTOR signaling pathway, and miR-16-5p and miR-29b-3p are involved in the PI3K-Akt signaling pathway." (PMID 36246123, 2022). "SIRT3 can also protect against sepsis-induced AKI by promoting autophagy via upregulating p-AMPK and downregulating phosphor-mammalian target of rapamycin (p-mTOR)." (PMID 34220520, 2021). "They used rapamycin, a specific antagonist of mTOR, to block mTOR signaling in a cecal legation and puncture- (CLP-) induced sepsis mouse model." (PMID 34257519, 2021). "The mTOR signaling was shown to enhance the secondary inflammation of CLP and to regulate the trained immunity of myeloid cells in sepsis." (PMID 32774145, 2020). "Therefore, the mTOR pathway might play a major role in cardiac dysfunction induced by sepsis." (PMID 30050390, 2018).
Sepsis (continued). "SIRT3 overexpression promoted autophagy, upregulated p-AMPK and downregulated p-mTOR in CLP mice, attenuating sepsis-induced AKI, tubular cell apoptosis, and inflammatory cytokine accumulation in the kidneys." (PMID 30487750, 2018). "The overexpression of SIRT3 promoted autophagy concomitant with p-AMPK, upregulation of p-mTOR downregulation and confirmed the involvement of AMPK/mTOR-related autophagy, in the protective effect of SIRT3 against sepsis-induced AKI." (PMID 30487750, 2018). "The study offers a potential mechanism of PI3K-Akt-mTOR-signaling pathway with PICK1 and autophagic activity in the setting of sepsis." (PMID 30402043, 2018). "We also discovered that MTOR was downregulated in patients with SRS1 and showed evidence of a sepsis eQTL." (PMID 26917434, 2016). "ERS in CD4+ T cells was enhanced in sepsis patients, particularly in elderly and non-survived individuals; ERS is strongly associated with mTOR-mediated autophagic-lysosomal disorder." (PMID 40933998, 2025). "It should also be noted that systemic sepsis-induced mortality was prevented by expressing MTOR in a lung EC-specific manner without affecting its expression in other organs." (PMID 39510184, 2024). "Therefore, we designed this experiment to explore the relationship between mTOR, autophagy, and CTLA4 in sepsis, the mechanism related was shown in the graphical abstract." (PMID 39104632, 2024). "To test and explore the viability of targeting mTOR to regulate CD4+ T-cell autophagy in sepsis as a way to minimize CTLA4 accumulation and hence alleviate CD4+ T-cell dysfunction, we employed rapamycin, a particular mTOR inhibitor, to corroborate the genetic approach's results." (PMID 39104632, 2024). "In the pathogenesis of sepsis, the PI3K/Akt/mTOR signaling pathway plays an important role." (PMID 38784395, 2024). "Drawing from two distinct knockout models, namely T-cell-specific TSC1 knockout (TSC1-KO) mice and T-cell-specific mTOR knockout (mTOR-KO) mice, we investigated the mTOR pathway's regulatory function on the autophagy level of CD4+ T cells and CTLA4 accumulation in sepsis." (PMID 39104632, 2024). "Results indicate that administration of adiponectin effectively reduces inflammatory factor levels in rats compared to controls, indicating its capacity to inhibit mTOR signaling via AMPK activation and subsequently alleviate hepatocyte apoptosis and liver injury during sepsis." (PMID 39664383, 2024). "The potential therapeutic effects of adiponectin on sepsis-induced hepatocyte injury have been investigated in recent studies, focusing on its interaction with AMP-activated protein kinase (AMPK) within the mechanistic target of mTOR signaling." (PMID 39664383, 2024). "In order to verify whether the AMPK/mTOR pathway was activated in sepsis-induced inflammation, we injected AMPK inhibitor Compound C or mTOR agonist MHY1485 into septic rats." (PMID 36694426, 2023). "The Akt-mTOR-HIF-1α signaling pathway and glycolytic-related enzymes are both targets for intervention in the Warburg effect, which open up new avenues for immunosuppressive therapy for sepsis." (PMID 37434129, 2023). "In summary, our study provided novel insight into the pathological mechanisms of sepsis-induced cardiomyopathy, and miR-130b-3p /ACSL4 and miR-130b-3p /AMPK/mTOR signaling may be considered the new targets for the treatment of septic cardiomyopathy." (PMID 37705752, 2023). "As far as we know, the upstream mechanisms by which mTOR regulates lymphocyte apoptosis in sepsis have not been elucidated." (PMID 35915740, 2022). "Adenosine monophosphate-activated protein kinase (AMPK) negatively regulates mTOR; thus, activation of AMPK could suppress mTOR activity, promote autophagy, limit the over-production of pro-inflammatory cytokines, and mitigate sepsis-induced kidney injury." (PMID 36188562, 2022).
Sepsis (continued). "To verify this hypothesis, we used T cell-specific knockout mTOR and TSC1 mice to create sepsis models using the classical CLP method to observe the effects of mTOR on ERS and the apoptosis of mice CD4+ T cells and the potential molecular regulatory mechanism." (PMID 35759162, 2022). "The expression of ERS marker proteins GRP78 and CHOP and mTOR pathway marker proteins p-mTOR, p70S6K, and p-p70S6K were evaluated in this study to explore the potential regulatory mechanism of mTOR in the ERS induced by sepsis." (PMID 35759162, 2022). "In a classic Sprague‒Dawley rat model of sepsis peritonitis, resveratrol significantly decreases LPS-induced expression of NF-κB, TNF-α, IL6, IL-1β, and TLR4 and increases the expression of p-PI3K, p-AKT, and p-mTOR in the myocardium." (PMID 36483739, 2022). "Curcumin has been reported in vitro as an mTOR inhibitor compound; however, there are no studies demonstrating this effect in experimental sepsis." (PMID 36365096, 2022). "This indicates that mTOR participates in and regulates ROS-mediated ERS-related CD4+ T cell apoptosis in sepsis, raising the possibility of mTOR becoming a new targeted treatment strategy for alleviating CD4+ T cell apoptosis and improving the immune status of those experiencing sepsis." (PMID 35915740, 2022). "To date, many studies have explored curcumin as an anti-inflammatory agent based on cytokine dosage and immune cell population in sepsis; however, there are no reports of its in vivo effect on the mTOR pathway in any pathology, especially in sepsis." (PMID 36365096, 2022). "Our observation that P529 partially rescued mortality in the TRALI model and prolonged survival in LPS-induced sepsis model suggests that inhibitors of PTP1B function, at least in part, through suppressing AKT/mTOR-mediated CXCR4 signaling, to promote neutrophil aging." (PMID 35866483, 2022). "We used this model to investigate whether mTOR could be pharmacologically used to regulate CD4+ T cell apoptosis thereby enhancing the immunity and improving the prognosis of patients with sepsis." (PMID 35915740, 2022). "This study successfully showed that TG attenuated sepsis-induced myocardial dysfunction by inhibiting myocardial autophagy via silencing the Phosphatase and tensin homolog (PTEN) expression and acting on the AKT/mTOR pathway." (PMID 33260422, 2020). "Also, mice with T-cell-specific TSC1 deletion had lower expression of T-bet and CD4+ T cell count indicating that the expression of T-bet required mTOR to participate in the regulation, and the regulation affected the CD4+ T cell count in Candida sepsis." (PMID 32431684, 2020). "HIPK2 overexpression reduced the sepsis-mediated increase in calpain 1 and cleaved Atg5 levels but did not affect mTOR levels." (PMID 30154452, 2018). "Our previous studies have found that the mTOR pathway in CD8 (+) T-cell was changed during the sepsis; however, there is little evidence to prove the relevance of mTOR in sepsis-induced cardiac dysfunction." (PMID 30050390, 2018). "In this article, we investigated the role of autophagy, mediated by a mammalian target of rapamycin (mTOR) and AMP-activated protein kinase (AMPK), in the protective effect of SIRT3, against sepsis-induced AKI, in a mouse model of cecal ligation and puncture (CLP)." (PMID 30487750, 2018). "Combined with our results showing that CLP inhibited the mTOR signaling pathway in cardiomyocytes, we believe that CLP-induced inhibition of mTOR signaling is beneficial for cardiomyocyte survival, leading to improvement of cardiac functions under sepsis." (PMID 30050390, 2018). "As such, the long known role of C5aR in sepsis, which signals through PI3Kγ, might reflect the central importance of the PI3K-Akt-mTOR axis." (PMID 29997622, 2018). "On the other hand, 7 of the 8 patients who were not on mTOR inhibitors died (5 due to cancer progression, 1 due to sepsis and 1 due to ischemic heart disease)." (PMID 29228580, 2017).